MOG (myelin oligodendrocyte glycoprotein)
Diseases named in the same sentence as MOG in open-access papers (continued):
Sharing a sentence is not in itself a finding about the gene and the disease.
neuromyelitis optica spectrum disorder (continued). "Ocular pathologies are relatively understudied sequelae of autoimmunity with ADON being the most prevalent visual complication in people with multiple sclerosis (pwMS), neuromyelitis optica spectrum disorder (NMOSD), and myelin oligodendrocyte glycoprotein antibody-associated diseases (MOG-AD)." (PMID 37128292, 2023). "White blood cell (WBC) count profiles in anti-aquaporin-4 antibody-positive neuromyelitis optica spectrum disorder (AQP4-NMOSD) and anti-myelin oligodendrocyte glycoprotein antibody-associated disease (MOGAD) are still unknown." (PMID 37081126, 2023). "The demyelinating diseases of the central nervous system include multiple sclerosis (MS), myelin oligodendrocyte glycoprotein (MOG) antibody-associated disease (MOGAD), neuromyelitis optica spectrum disorder (NMOSD), and acute disseminated encephalomyelitis (ADEM)." (PMID 36851302, 2023). "Moreover, the safety of SARS-CoV2 vaccines has been highlighted in adult MS and in adult patients with aquaporin-4-IgG neuromyelitis optica spectrum disorder (AQP4-IgG+NMOSD) and myelin oligodendrocyte glycoprotein associated disease (MOGAD)." (PMID 36761740, 2023). "Therefore, we aimed to investigate the prevalence of PHOMS in patients with (i) aquaporine-4-IgG-positive (AQP4) neuromyelitis optica spectrum disorders (AQP4 + NMOSD) and (ii) myelin oligodendrocyte glycoprotein-IgG (MOG)-associated disease (MOGAD)." (PMID 36245037, 2023). "Anti-N-methyl-d-aspartate receptor encephalitis (NMDARe), a common autoimmune encephalitis, can be accompanied by demyelinating disorders, including multiple sclerosis (MS), neuromyelitis optica spectrum disorder (NMOSD), and myelin oligodendrocyte glycoprotein antibody-associated disease (MOGAD)." (PMID 35837405, 2022). "In addition, a concomitant involvement of the peripheral nervous system (PNS) has been described either in association with AQP4 antibodies-positive neuromyelitis optica spectrum disorder (NMOSD), or MOG-associated disease." (PMID 36498887, 2022). "Inflammatory myelopathies can be recognized in the context of numerous immune-mediated disorders, including multiple sclerosis (MS), aquaporin-4(AQP4)-IgG-positive neuromyelitis optica spectrum disorders (AQP4+NMOSD), and myelin oligodendrocyte glycoprotein (MOG) antibody-associated disease (MOGAD)." (PMID 36330423, 2022). "Initially, it was suspected that her condition was secondary to alternative inflammatory process such as neuromyelitis optica or myelin oligodendrocyte glycoprotein antibody demyelination due to bilateral involvement of her optic discs, but was later on ruled out by laboratory work up." (PMID 35321665, 2022). "Therefore, neuromyelitis optica with evidence of MOG antibodies is currently regarded as another, but separate, entity belonging to the MOG-antibody associated diseases (MOGAD)." (PMID 35456972, 2022). "Multiple sclerosis (MS), aquaporin-4-antibody-positive neuromyelitis optica spectrum disorder (AQP4-Ab-positive NMOSD), and myelin oligodendrocyte glycoprotein antibody-associated disease (MOGAD) are distinct inflammatory demyelinating disorders of the central nervous system." (PMID 35837405, 2022). "The most common Antibody (Ab)-mediated disorders of the central nervous system (CNS) are aquaporin-4 antibody neuromyelitis optica spectrum disorders (AQP4+NMOSD), myelin-oligodendrocyte glycoprotein antibody-associated disease (MOGAD), and autoimmune encephalitis (AE)." (PMID 36601293, 2022). "This is in addition to the emergence of a new phenotype associated with MOG-Ab called MOG-associated disorder (MOGAD) in pediatric patients with acute demyelinating encephalomyelitis and patients with a form of neuromyelitis optica known as MOG-associated disorder (MOGAD)." (PMID 36232832, 2022).
neuromyelitis optica spectrum disorder (continued). "Aquaporin 4 antibodies have been found in those with lupus and optic neuropathy and myelitis and represent a treatable condition, neuromyelitis optica, and so are clinically useful investigations, and also antibodies to myelin oligodendrocyte glycoprotein (MOG)." (PMID 34299237, 2021). "Another 26-year-old man had myelin oligodendrocyte glycoprotein antibody-positive neuromyelitis optica, presenting as bilateral optic neuritis and longitudinal extensive transverse myelitis a few days after COVID-19 symptoms onset and responsive to methylprednisolone pulse therapy." (PMID 33777042, 2021). "Various types of cell-based therapies may hold promise for treatment of potentially severe autoimmune neurological diseases, including neuromyelitis optica spectrum disorders (NMOSD) and myelin oligodendrocyte glycoprotein antibody-associated disease (MOGAD)." (PMID 34360690, 2021). "Background and purpose: Immunoadsorption (IA) is an antibody-depleting therapy used to treat neuromyelitis optica spectrum disorder (NMOSD) associated to antiaquaporin 4 (anti-AQP4-IgG) and antimyelin oligodendrocyte glycoprotein (anti-MOG-IgG) serum autoantibodies." (PMID 33763015, 2021). "While Multiple Sclerosis (MS) is the most common cause, there is also a spectrum of relatively rare neuroinflammatory and neurodegenerative diseases such as Neuromyelitis optica spectrum disorder (NMOSD) and myelin oligodendrocyte glycoprotein (MOG)-IgG antibody associated disease (MOGAD)." (PMID 35140707, 2021). "Immunosuppressants could be effective in reducing the recurrence rate for neuromyelitis optica spectrum disorder and MOG antibody-related diseases, but there have been few studies addressing this issue focusing on the changes in ophthalmic parameters." (PMID 33628473, 2020). "Multiple Sclerosis (MS) needs to be differentially diagnosed from rare MS variants, Acute Disseminated Encephalomyelitis (ADEM), the range of Neuromyelitis Optica Spectrum Disorders (NMOSDs), Myelin Oligodendrocyte Glycoprotein (MOG) antibody disease and other systemic inflammatory diseases." (PMID 33182495, 2020). "Furthermore, previous studies have indicated that CSF MBP levels are elevated in anti-MOG antibody-positive patients with neuromyelitis optica spectrum disorder (NMOSD), transverse myelitis, and acute disseminated encephalomyelitis (ADEM)." (PMID 33391163, 2020). "In the past few years, growing clinical, immunological and histopathological evidence suggests that MOG-EM can now be considered as a clearly distinct disease entity from both multiple sclerosis (MS) and aquaporin-4-positive neuromyelitis optica spectrum disorder (NMOSD)." (PMID 32055995, 2020). "The first one is neuromyelitis optica in which an antibody response against aquaporin-4 targets and destroys astrocytes, the second, likely distinct entity embraces a group of patients containing antibodies against myelin oligodendrocyte glycoprotein." (PMID 30800132, 2019). "MOG-IgG seropositivity has been reported in several demyelinating diseases, including relapsing opticospinal syndromes [in the neuromyelitis optica spectrum disorders (NMOSD) and less frequently, in multiple sclerosis (MS)], but it has rarely been associated with the progressive course of disease." (PMID 29867746, 2018). "Antibodies to the myelin oligodendrocyte glycoprotein (MOG) are associated with a subset of inflammatory demyelinating diseases of the central nervous system such as acute disseminated encephalomyelitis and neuromyelitis optica spectrum disorders." (PMID 29070051, 2017). "While complement inhibition significantly reduces the relapse rate in neuromyelitis optica spectrum disorders (NMOSDs), no clear consensus has been reached regarding the role of complement in myelin oligodendrocyte glycoprotein antibody-associated disease (MOGAD) and multiple sclerosis (MS)." (PMID 41661329, 2026).
neuromyelitis optica spectrum disorder (continued). "Under certain pathological conditions, they may also secrete antibodies to self-antigens and cause autoimmune diseases such as rheumatoid arthritis (RA), systemic lupus erythematosus (SLE), myelin oligodendrocyte glycoprotein antibody-associated disease (MOGAD) and Neuromyelitis Optica (NMO)." (PMID 39772034, 2024). "Optic neuritis secondary to causes other than MS, like neuromyelitis optica (NMO – anti-aquaporin 4 related disease) and anti-MOG disease have been reported to have ffERG evidence of inner retinal dysfunction in some cases, although it remains uncertain whether specific to those disorders." (PMID 38862643, 2024). "Additionally, ancillary testing including brain magnetic resonance imaging (MRI), spinal MRI, cerebrospinal fluid studies, and AQP4 and MOG antibody tests may be performed to rule-out multiple sclerosis for neuromyelitis optica in cases with ON24,25." (PMID 38429319, 2024). "Myelin oligodendrocyte glycoprotein (MOG) antibody immunoglobulin G (IgG)-associated disease (MOGAD) has clinical and pathophysiological features-like but distinct from those of aquaporin-4 antibody (AQP4-IgG)-positive neuromyelitis optica spectrum disorders (AQP4-NMOSD)." (PMID 39456143, 2024). "A lack of pathologic specificity solely to MS for LME could be expected, given prior work showing prevalent findings of LME in other autoimmune conditions such as neurosarcoidosis, neuromyelitis optica, myelin oligodendrocyte glycoprotein antibody disorder (MOGAD), and Susac syndrome." (PMID 38809920, 2024). "However, ON may have other important causes including neuromyelitis optica spectrum disorder (NMOSD), myelin oligodendrocyte glycoprotein (MOG)-IgG, systemic vasculitis, sarcoidosis." (PMID 36741486, 2023). "Besides ATM, other CNS demyelinating events, like multiple sclerosis (MS), neuromyelitis optica spectrum disorder, and myelin oligodendrocyte glycoprotein antibody disease, have occurred after administration of all types of approved COVID-19 vaccines, including the mRNA versions." (PMID 36005648, 2022). "Myelin oligodendrocyte glycoprotein-IgG-associated disorder (MOGAD) is a nervous system (NS) demyelination disease and a newly recognized distinct disease complicated with various diseases or symptoms; however, MOGAD was once considered a subset of neuromyelitis optica spectrum disorder (NMOSD)." (PMID 35370624, 2022). "MOG antibody-associated disease has similarity to Neuromyelitis Optica Spectrum Disorders (NMOSD) in terms of clinical and imaging phenotypes, suggesting that patients within the aquaporin 4 (AQP4) antibody seronegative cohort become suspects for MOG antibody-associated disease." (PMID 33510701, 2020). "Therefore, our findings cannot be generalized to patients with atypical optic neuritis, including neuromyelitis optica and myelin oligodendrocyte glycoprotein–associated optic neuritis or those who would not have met the ONTT inclusion criteria." (PMID 32379333, 2020). "Most experts now consider MOG-IgG-associated encephalomyelitis (MOG-EM) a disease entity in its own right, immunopathogenetically distinct from both classic multiple sclerosis (MS) and aquaporin-4 (AQP4)-IgG-positive neuromyelitis optica spectrum disorders (NMOSD)." (PMID 29724224, 2018). "Moreover, the latest research suggests that MOG-IgG might be involved in immunopathogenesis of neuromyelitis optica." (PMID 26950113, 2016). "Antibodies against myelin oligodendrocyte glycoprotein (MOG) have been identified in a subgroup of pediatric patients with inflammatory demyelinating disease of the central nervous system (CNS) and in some patients with neuromyelitis optica spectrum disorder (NMOSD)." (PMID 25889963, 2015). "Aquaporin-4 neuromyelitis optica spectrum disorder (AQP4-NMOSD) often coexists with other autoimmune diseases (AIDs), whereas such comorbidities are less common in myelin oligodendrocyte glycoprotein antibody disease (MOGAD)." (PMID 40495001, 2025).
neuromyelitis optica spectrum disorder (continued). "Testing for anti-neuromyelitis optica (NMO) and anti-myelin oligodendrocyte glycoprotein (MOG) antibodies in the serum in two reference laboratories (University Hospital of Zurich, University Hospital of Basel) with different assays was negative." (PMID 40161152, 2025). "It presents with sudden and often painful vision loss and can be associated with demyelinating diseases like multiple sclerosis (MS), neuromyelitis optica spectrum disorder (NMOSD), and myelin oligodendrocyte glycoprotein antibody disease (MOGAD)." (PMID 40606143, 2025). "Neuromyelitis Optica Spectrum Disorder (NMOSD) is a chronic autoimmune neuroinflammatory disease, typically characterized by antibodies against aquaporin 4 (AQP4-IgG) or myelin oligodendrocyte glycoprotein (MOG-IgG)." (PMID 41350239, 2025). "In this study, we investigated a large cohort of patients with neuromyelitis optica spectrum disorders (NMOSD), pre‐classified based on serum IgG autoantibodies against AQP4 and MOG." (PMID 40103346, 2025). "Diagnosis of DMD included analysis of blood cells/hemogram, CSF for protein levels, antibody detection in serum or CSF for OCBs: oligoclonal bands; neuromyelitis optica (NMO) antibodies and/or myelin oligodendrocyte glycoprotein (MOG) antibodies." (PMID 39456253, 2024). "NMO/NMOSD: neuromyelitis optica/neuromyelitis optica spectrum disorder; MOGAD: myelin oligodendrocyte glycoprotein antibody disease." (PMID 39006634, 2024). "Although neuromyelitis optica spectrum disorders (NMOSD) and myelin oligodendrocyte glycoprotein antibody disease (MOGAD) are rare diseases, they pose a significant burden on both society and the healthcare system." (PMID 39717684, 2024). "Several conditions mimicking CLIPPERS have been identified, including myelin oligodendrocyte glycoprotein antibody disease (MOGAD), and neuromyelitis optica (NMO)." (PMID 39130962, 2024). "Even though most clinical pictures of this condition are similar to the presentation of neuromyelitis optica spectrum disorder (NMOSD), most experts consider MOG-AD as a distinct entity with different immune system pathology." (PMID 38975430, 2024). "There have been many advancements in the field of neuromyelitis optica and neuromyelitis optica spectrum disorder since the discovery of aquaporin-4 (AQP4) and myelin oligodendrocyte glycoprotein antibodies." (PMID 37581199, 2023). "We performed a critical targeted review of the diagnoses of the most prevalent demyelinating disorders: multiple sclerosis (MS), neuromyelitis optica spectrum disorders (NMOSD) and myelin oligodendrocyte glycoprotein antibody disease (MOGAD)." (PMID 35976299, 2022). "One such biomarker in the spinal fluid is myelin oligodendrocyte glycoprotein (MOG-IgG) and aquaporin-4 (AQP4), which are used to identify neuromyelitis optica spectrum disorders." (PMID 35187013, 2022). "Together with neuromyelitis optica spectrum disorders (NMOSD), MOG-EM is the most important differential diagnosis of multiple sclerosis (MS)." (PMID 35737110, 2022). "BN rats also have a strong anti‐MOG antibody response, which may also demonstrate the relevance of this model for other neurological diseases such as pediatric MS, subgroups of neuromyelitis optica and cases of anti‐NMDA‐receptor encephalitis where such antibodies are present." (PMID 30578556, 2019). "In comparison to children with AQP4-positive neuromyelitis optica spectrum disorder (NMOSD), those with MOG-AD tend to be younger, less likely to present with area postrema syndrome, but more likely to present with ADEM." (PMID 30569382, 2019). "It is discussed whether MOG-IgG define a separate disease entity tentatively called MOG-IgG-associated diseases, MOG-IgG autoimmunity or MOG-IgG seropositive encephalomyelitis rather than being part of several autoimmune disorders, especially neuromyelitis optica spectrum disorders (NMOSD)." (PMID 31345223, 2019).
neuromyelitis optica spectrum disorder (continued). "The role that anti‐MOG antibodies might be playing in this disease model is intriguing due to their association with other neurological conditions such as pediatric MS, neuromyelitis optica in AQP‐4 antibody‐negative cases and occasionally anti‐NMDA‐receptor encephalitis." (PMID 30578556, 2019). "Neuromyelitis optica spectrum disorders (NMOSD) and anti-myelin oligodendrocyte glycoprotein (anti-MOG) syndromes are immune-mediated inflammatory conditions of the central nervous system (CNS) that frequently involve the optic nerves and the spinal cord." (PMID 31212763, 2019). "Neuromyelitis optica spectrum disorder (NMOSD) and anti-myelin oligodendrocyte glycoprotein (anti-MOG) syndromes are immune-mediated inflammatory conditions of the central nervous system that frequently involve the optic nerves and the spinal cord." (PMID 31212763, 2019). "We characterized a unique group of patients with neuromyelitis optica spectrum disorder (NMOSD) who carried autoantibodies of aquaporin-4 (AQP4) and myelin-oligodendrocyte glycoprotein (MOG)." (PMID 26920678, 2016). "Serological testing for neuromyelitis optica spectrum disorder (NMOSD)-associated aquaporin-4 (AQP4) antibodies and myelin oligodendrocyte glycoprotein (MOG) antibodies also returned negative results." (PMID 40896010, 2025). "The absence of MOG-IgG and AQP4-IgG in serological tests effectively excluded both neuromyelitis optica spectrum disorder and MOG-associated encephalomyelitis." (PMID 40426809, 2025). "MOG-IgG can be detected in AQP4-IgG negative neuromyelitis optica spectrum disorder and ON, and some of these patients will develop a recurrent form of the disease." (PMID 41235231, 2025). "The absence of brain lesions on the MRI supported the exclusion of multiple sclerosis (MS), while the lack of oligoclonal bands in the CSF and negative anti-AQP4 and anti-MOG antibody results argued against neuromyelitis optica spectrum disorder (NMOSD)." (PMID 41002717, 2025). "As was necessary in all three of our cases, the increased sensitivity is counterbalanced by the need for stringent exclusion of disease mimics such as neuromyelitis optica spectrum disorder (NMOSD) and myelin oligodendrocyte glycoprotein antibody disease (MOGAD)." (PMID 41446483, 2025). "Cerebral MRI showed nonspecific gliotic patches that were not suggestive of multiple sclerosis, neuromyelitis optica spectrum disorder (NMOSD), or myelin oligodendrocyte glycoprotein-associated disease (MOGAD)." (PMID 39781309, 2024). "Neuromyelitis optica spectrum disorder and anti-MOG antibody testing were negative, while CSF analysis revealed oligoclonal bands." (PMID 39618752, 2024). "Conversely, ON subtypes are termed atypical ON if the underlying etiology of the condition arises from neuromyelitis optica (NMO), NMOSD, MOG-IgG ON, or other pathologies that are not relevant to the discussion of this review." (PMID 38618469, 2024). "Neuromyelitis optica spectrum disorders (NMOSD) and myelin oligodendrocyte glycoprotein antibody disease (MOGAD) are both immune-mediated demyelinating disorders frequently involving optic nerve and/or spinal cord causing a wide range of neurological disabilities." (PMID 39717684, 2024). "Serum and cerebrospinal fluid aquaporin-4 antibody testing and serum myelin oligodendrocyte glycoprotein testing were negative, effectively lowering seropositive neuromyelitis optica spectrum disorder on the list of differential diagnoses." (PMID 39720826, 2024). "MOG immunoglobulin G (IgG) antibodies in CSF were positive, while neuromyelitis optica (NMO) IgG antibodies were negative by cell-based assay (CBA)." (PMID 39156322, 2024). "Data on peripheral blood mononuclear cells (PBMCs) characteristics of aquaporin‐4 (AQP4)‐IgG seropositive neuromyelitis optica spectrum disorder (NMOSD) and myelin oligodendrocyte glycoprotein antibody‐associated disease (MOGAD) are lacking." (PMID 38334017, 2024).